PIK3CA (phosphatidylinositol-4,5-bisphosphate 3-kinase catalytic subunit alpha)
Diseases named in the same sentence as PIK3CA in open-access papers (continued):
Sharing a sentence is not in itself a finding about the gene and the disease.
tumor (continued). "CTCs and disaggregated tumor cells were individually retrieved from slides using the CytePicker® module for sequence analysis of a BC-PDX tumor-specific PIK3CA mutation." (PMID 30871481, 2019). "Different subtypes were notable for particular molecular pathogenetic features; for example, EBV-positive tumours harboured recurrent PIK3CA mutations, along with amplifications involving JAK2, CD274 (encoding PD-L1) and PDCD1LG2 (encoding PD-L2)." (PMID 31790410, 2019). "Subsequent withdrawal of doxycycline resulted in a loss of mutant PIK3CA expression and led to rapid and dramatic tumour regression, thereby demonstrating that maintenance of the established lung tumours required continued expression of p110αH1047R." (PMID 31018529, 2019). "PIK3CA E545K mutation in tumor tissues was correlated with poor/moderate differentiation and late clinical stage." (PMID 32099598, 2019). "One possible mechanism is that the PIK3CA/H1047R mutation is a stronger driver of tumor development than other types of PIK3CA mutations such as E542K and E545K." (PMID 31088410, 2019). "ARQ-092 has been shown to exhibit anti-tumour activity in a variety of solid and haematological tumours harbouring activating PIK3CA mutations, and promising clinical activity in patients harbouring AKTE17K mutations." (PMID 31540244, 2019). "While loss of PTEN is often correlated with endometrioid histology, low tumor grade, and favorable prognosis, PIK3CA is associated with high tumor grade." (PMID 31367798, 2019). "Low-grade carcinoma usually have PIK3CA mutation and it progresses into high grade tumor after in inactivation CDKN2A." (PMID 31665050, 2019). "Among mutations specific to the m-PET-high tumor were a gain of function mutation of PIK3CA (T1258C) and a truncating mutation of RB1 (splice site, chromosome 13: 49047536 del)." (PMID 30760837, 2019). "The tumor microenvironment of PIK3CA-mutated tumors was infiltrated with relatively more CD8-positive cells compared to wild-type tumors (p = 0.038)." (PMID 31391067, 2019). "The HRAS and PIK3CA mutation had significant association with site of tumor, i.e., lower lip (p = 0.002) and lower alveolus (p = 0.004)." (PMID 31775759, 2019). "The prognostic effect of PIK3CA alterations was assessed in 312 patients in the placebo arm of the correlative cohort who had sufficient tumor material for the testing of PIK3CA mutations and PIK3CA amplification." (PMID 30867034, 2019). "In the present study, tumor shrinkage was observed in two patients with PIK3CA mutation in the helical domain, which is a hotspot for PIK3CA mutations." (PMID 31227862, 2019). "Previous mutational analysis of the PIK3CA gene performed on all tumor samples demonstrated that 22 patients (23.7%) harbored a PIK3CA hot spot mutation in exon 9 (n = 21) or exon 20 (n = 1)." (PMID 31766658, 2019). "PIK3R1 encodes the p85 regulatory subunit-α, which plays a tumor suppressor role, regulating and stabilizing the p110α catalytic subunit encoded by the oncogene PIK3CA." (PMID 31119098, 2019). "Disparity in the PIK3CA mutation status between CTCs and matched primary tumours was higher than that of HER2 and concerned 66% of the cases." (PMID 30691008, 2019).
tumor (continued). "Thirty-three tumors (15%) harbored a PIK3CA mutation including one tumor with two PIK3CA mutations p.D725 N and p.H1047Y." (PMID 31036005, 2019). "Gene expression was modeled as a function of tumor and the PIK3CA mutation considered as random factors for each other." (PMID 31842489, 2019). "To date, clinical implications of the PIK3CA N345K variant remain insufficiently investigated; however, everolimus treatment resulted in the shrinkage of tumor lesions and decreased the levels of tumor markers." (PMID 31583146, 2019). "All PIK3CA amplicons – from the primary tumor, CTCs and lung nodule – contained the T1035A mutation supporting a common clonal origin of the PDX model cells." (PMID 30871481, 2019). "TNBC tumours commonly have either activating mutations or amplifications of PIK3CA, BRAF, KRAS and/or EGFR and/or PTEN loss, causing abnormal activity of the Raf/MAPK/ERK or PI3K/Akt/mTOR pathway." (PMID 31527768, 2019). "In a HNSCC cell line (Cal-33) and a patient-derived xenograft model, both harboring H1047R mutation in PIK3CA, administration of alpelisib using nanoparticles induced inhibition of tumor growth and sensitization to radiation." (PMID 31093356, 2018). "Further treatment of these HER2-positive and PIK3CA-mutated tumor xenografts with AKT inhibitor AZD5363 subsequently rendered the xenografts to be responsive to trastuzumab treatment again." (PMID 30157855, 2018). "Serum samples from all four patients (patient nos 24, 25, 26, and 27) showed a decreased level of PIK3CA‐mutated ctDNA in the second and, for one, third serum sample, suggesting tumor shrinkage during treatment." (PMID 29689598, 2018). "Of the characteristics analyzed, the only significant association was between the presence of mutated PIK3CA and tumor differentiation grade (well/moderate vs. poor/undifferentiated, odds ratio [OR] 0.37, 95% CI 0.17–0.79, p= 0.011)." (PMID 29484141, 2018). "These ESR1 and PIK3CA mutations coincide with increasing CA 27–29 levels in the blood, suggesting rapid genomic evolution and tumor progression." (PMID 30470782, 2018). "We found 83% of patients with PIK3CA mutation in the metastatic tumor tissue also had detectable PIK3CA mutations in serum ctDNA." (PMID 29689598, 2018). "These tumor-associated PIK3CA mutations lead to constitutive p110α activation and oncogenic transformation in multiple cancers." (PMID 29636477, 2018). "Of the 24 patients with detectable PIK3CA mutations in the metastatic tumor tissue, 20 (83%) had similar mutations detectable in corresponding ctDNA from serum." (PMID 29689598, 2018). "Analysis of participant 3's FFPE tumour tissue DNA revealed a PIK3CA mutation (PIK3CA_ p.S326F_ COSM16668843/4) at a VAF of 1%." (PMID 29535826, 2018). "PIK3CA tumor mutations were associated with significant better disease-free survival in postmenopausal women." (PMID 29707142, 2018). "CTCs count and ESR1/PIK3CA mutations in circulating tumor DNA were performed and correlated with TK1 activity." (PMID 29662653, 2018). "Although only four patients with PIK3CA mutation in metastatic tumor tissue were followed with serial serum samples, all showed changes in PIK3CA ctDNA levels that correlated with treatment response according to imaging assessments." (PMID 29689598, 2018). "AFs of concordant point mutations and indels in EGFR, KRAS, and PIK3CA ranged from 0.3 to 52% in tumor tissue DNA and in plasma cfDNA from 0.2 11.6%." (PMID 29441349, 2018).
tumor (continued). "It is expected that PIK3CA mutations would imply poor clinical outcome, because the presence of oncogene activation leads to aggressive tumor behavior." (PMID 30115035, 2018). "Overall, 5 total patients presented with somatic variants in PIK3CA (incidence of 5/7, 71%) in at least tumor or blood." (PMID 30470782, 2018). "The most common mutation detected in primary tumor tissues was PIK3CA (6 patients, 37.5%), followed by ERBB2, mTOR and INPP4B (5 patients for each one, 31.25%)." (PMID 30167082, 2018). "AR + /FOXA1 + tumours (42.4%) were more frequently: found in older patients, lobular, of lower nuclear grade, with more frequently PIK3CA mutations; exhibited less frequently BRCA1 promoter methylation, defects of PTEN and PD-L1 expression than others." (PMID 29880907, 2018). "PIK3CA mutation in tumor tissues was correlated with lower histological grade and late clinical stage." (PMID 29970892, 2018). "The biomarker analysis set for predictive genomic markers (KRAS, NRAS, BRAF, or PIK3CA mutations) included 46 subjects with tumour tissue sequenced." (PMID 30425349, 2018). "OncoKB level 4 data lists all available histological tumor types as possibly actionable for PIK3CA activating mutations." (PMID 30442178, 2018). "In a phase I clinical trial, the PI3K inhibitor temporarily decreased the size of the tumor in a patient with EGFR L858R/T790M/PIK3CA mutation after progression during treatment with erlotinib." (PMID 30445769, 2018). "Complete and partial responses to BRAF inhibition have been observed in patients with complete loss of PTEN tumour expression and with PIK3CA tumour-associated activating mutations." (PMID 30237495, 2018). "PIK3CA has been previously reported to be mutated at a high frequency in specific TCW-containing helical motifs across a number of tumor types." (PMID 29435122, 2018). "For instance, the potential neoantigen based on BRAF V600E mutation and HLA-A03:01 exists in 117 tumor samples, and corresponding neoantigens based on several mutations of KRAS and PIK3CA are also shared in more than 40 tumor samples." (PMID 30223042, 2018). "Our pooled analysis showed that PIK3CA dysregulation is associated with poorer tumor differentiation and worse OS among GC patients, indicating that PIK3CA is a prognostic biomarker for GC patients." (PMID 29484141, 2018). "The mutational status (KRAS and PIK3CA genes) of the primary tumour (T11) and its matched metastasis (M11) was confirmed by Sanger analysis." (PMID 29416628, 2018). "The second most common mutated gene in our cohorts of patients was PIK3CA, which was distributed across all tumor types." (PMID 29854313, 2018). "Specifically, 40% of hormone dependent cancers harbor activating mutations in PIK3CA, making this gene an attractive candidate for tumor monitoring by tumor-specific mutation quantification in plasma samples." (PMID 28330468, 2017). "In ESCCs, we identified amplification or mutation of EGFR in 19% of tumours and alterations of PIK3CA, PTEN or PIK3R1, all of which are believed to activate the PI3K pathway, in 24% of tumours." (PMID 28052061, 2017). "The proportion of observed agreement between COBAS and QuantStudio3D system when assessing the PIK3CA mutation status in the archival tumor was 100% (K = 1)." (PMID 28330468, 2017). "The atypical subtype was characterized by enrichment of HPV-positive tumor and activating mutations in exon 9 that contain PIK3CA." (PMID 29340043, 2017). "Patient EC-3 had two PIK3CA mutations in the primary tumor, but only one of these mutations was detected in its corresponding metastasis." (PMID 28860563, 2017).
tumor (continued). "GDC-0032 exhibits potent anti-proliferative and anti-tumor activities in head and neck squamous cell carcinoma and uterine serous carcinomas cell lines and xenografts with PIK3CA mutations or amplifications." (PMID 28592260, 2017). "The present study serves this purpose by improving our understanding of the use of tumor PIK3CA mutation status for prediction of patient response to aspirin therapy." (PMID 29152088, 2017). "For instance whole exome sequencing on DNA from 39 patients reported that PIK3CA was mutated only five times in four patients and, importantly, none of these mutations were the “classical” hotspot mutations observed in other tumour types." (PMID 28696382, 2017). "Previous data therefore indicate it is possible that PIK3CA mutations lead to different effects on downstream signal transducers in different tumor models." (PMID 28532501, 2017). "In contrast, the PIK3CA oncogene was frequently mutated in both tumor types, but was more often the target of APOBEC-mediated deamination in the HPV-active tumors." (PMID 28077784, 2017). "In our model including all tumor types, both PIK3CA and PTEN mutations were associated with increased sensitivity (P = 0.041 and P = 0.016, respectively; Wald test)." (PMID 28903445, 2017). "Although currently published (pre-)clinical data report contradictory results, KRAS and PIK3CA mutation status have previously been associated with respectively resistance and sensitivity to mTOR inhibition in particular tumor types." (PMID 28903445, 2017). "Further validation of the FFL (PDGF/FLT1/SHC1) as predictive factor for the survival of the PIK3CA-mutated luminal-A tumor patients is necessary." (PMID 28392480, 2017). "PIK3CA mutations lead to constitutive activation of the p110a protein kinase and its downstream signaling pathway, thus resulting in tumor cell proliferation and survival." (PMID 28002810, 2017). "In one case (from now on patient 3) changes in PIK3CA mutation quantification were in the opposite direction than tumor markers." (PMID 28330468, 2017). "In our study, we observed that none of the two POLE‐positive tumors presented NRAS or BRAF mutations, but tumor T286 exhibited the p.Glu542Lys PIK3CA mutation and tumor T368 displayed the p.Lys117Asn KRAS mutation." (PMID 29072370, 2017). "Multiple logistic regression analysis indicated that pathological grade, tumor size at diagnosis and PR status were positively associated with PIK3CA mutations." (PMID 28729728, 2017). "High-throughput mutational analysis of human tumor samples revealed that PIK3CA is frequently affected by cancer-specific somatic mutations in the heterozygous state." (PMID 28353628, 2017). "For these analyses, we evaluated the basal and on-treatment cfDNA status of the four patients in our cohort who carried a prior to treatment tumor mutation in BRAF or BRAF/PIK3CA." (PMID 27852040, 2017). "In summary, taking a systems approach based on the cancer hallmark network framework, we found that the FFL (PDGF/FLT1/SHC1) is significantly enriched in the PIK3CA-mutated luminal-A tumor patients." (PMID 28392480, 2017). "PIK3CA mutation rate in ASCC ranged from 20% in specimens from the primary tumor site to 37% in samples from regional metastases." (PMID 28556593, 2017). "As for plasma samples, Of the 15 PIK3CA mutations detected in tumors by ddPCR, 14 of the corresponding mutations were detected in pre-surgical plasma tumor DNA (ptDNA), and half of the patients had detectable ptDNA after surgery." (PMID 29088906, 2017). "For instance this led to trials of p110α inhibitors in cancers harbouring activating PIK3CA mutations or p110β inhibitors in tumours driven by PTEN loss, as this specific isoform was reported to be critical in this context." (PMID 28696382, 2017).
tumor (continued). "For the single patient (patient 9) who recurred despite not having detectable mutDNA at this time-point in any peripheral sample, the tumour had a PIK3CA E545K mutation that was present at an AF of only 0.7%." (PMID 28717136, 2017). "This was consistent with data from a cohort of metastatic cSCC (29 cSCC lymph node metastases) that identified a PIK3CA P471L mutation in some of these tumours." (PMID 28696382, 2017). "Whole exome sequencing also showed that P5 tumors harbored many of the same gene mutations present in the original patient tumor, one of which was a PIK3CA mutation." (PMID 28903344, 2017). "We demonstrated that tumor samples from the donor patient and those from the mouse model (P5 as representative) were both positive for a PIK3CA mutation." (PMID 28903344, 2017). "The specific site of a PIK3CA mutation is potentially an important predictive indicator for tumor growth and response to treatment." (PMID 28556593, 2017). "According to WES results, a PIK3CA mutation was detected in both the P5 model tumor and the original patient tumor, Sanger sequencing was used to confirm the PIK3CA mutation in the original patient tumor." (PMID 28903344, 2017). "PIK3CA activating mutations are common in several tumor types and can potentially confer resistance to anti-receptor tyrosine kinase therapy." (PMID 28532501, 2017). "It is noteworthy that tumor shrinkage of >20% was observed in 2 patients with confirmed PIK3CA mutation." (PMID 28899363, 2017). "In conclusion, PIK3CA mutations were associated with increased tumor aggressiveness, especially in locoregional disease, and Akt activation in GC." (PMID 29207615, 2017). "Both tumours harbour a PIK3CA hotspot activating mutation (missense H1047R) and express high levels of P-selectin." (PMID 28194032, 2017). "In the present study, we sought to investigate the anti-tumor activity of everolimus in solid tumors with specific genotypes such as PIK3CA amplification/mutation and/or PTEN loss." (PMID 28330462, 2017). "WES results showed that our patient tumor sample had a PIK3CA mutation, and this was also true of the PDX model." (PMID 28903344, 2017). "Somatic PIK3CA mutations observed in tumours are oncogenic and result in increased catalytic PI3K kinase activity." (PMID 28393905, 2017). "Of the patients who did not experience a clinical benefit, three carried BRAF mutations, and one carried BRAF/PIK3CA mutations in their tumor tissues prior to treatment." (PMID 27852040, 2017). "Using this model, we show that mutated Pik3ca is a weak oncogene on its own, but that it can cooperate with other oncogenic lesions, such as heterozygous loss of the Apc tumour suppressor." (PMID 29170395, 2017). "Multivariate analysis (Cox proportional hazards model) was also used to assess the influence of COX-2 mRNA level on MFS, together with histological grade, lymph-node status, tumor size, estrogen and progesterone receptor status and PIK3CA mutations." (PMID 27835884, 2016). "Similar to ESR1, a slightly higher proportion of patients with luminal A tumours had PIK3CA mutations in ctDNA compared with patients with luminal B tumours (44%, 44/100 versus 38%, 17/45)." (PMID 27174596, 2016). "The EBV-positive tumours have been correlated with PIK3CA mutations; high levels of DNA hypermethylation; and amplification of JAK2, PD-L1, and PDCD1LG2." (PMID 27514667, 2016). "The pooled NLR of 0.14 suggests that patients with negative PIK3CA mutation in cfDNA still have 14% possibility to have PIK3CA mutation in their tumor sample." (PMID 27336598, 2016). "ER+ tumours had more PIK3CA mutations in codons 345 (62 out of 942 ER+, 2 out of 162 ER−; P=0.003396, Fisher's exact test) and codons 542 or 545 (helical domain; 259 out of 942 ER+, 32 out of 162 ER−; P=0.04245)." (PMID 27161491, 2016). "Specific knockdown of PIK3CA inhibited proliferation, migration, anchorage-independent growth and in vivo tumor growth of cells with PIK3CA mutations." (PMID 27465249, 2016).